CFTR (CF transmembrane conductance regulator)
Diseases named in the same sentence as CFTR in open-access papers (continued):
Sharing a sentence is not in itself a finding about the gene and the disease.
vitamin D deficiency (2 papers, 2021). A nutritional condition produced by a deficiency of VITAMIN D in the diet, insufficient production of vitamin D in the skin, inadequate absorption of vitamin D from the diet, or abnormal conversion of vitamin D to its bioactive metabolites. "The sub-group analyses using chi-square tests assessed the independence between vitamin D deficiency and CFRD risk factors, including sex, CFTR mutation status (F508del homozygous, F508del heterozygous, or no F508del mutation), and pancreatic enzyme usage." (PMID 34836301, 2021).
abortion (1 paper, 2014). the ending of pregnancy by removing a fetus or embryo before it can survive outside the uterus. "Overexpression of CFTR protein and decreased expression of ENaC-α protein was detected in the abortion-prone CBA×DBA/2 decidua tissues (P<0.05)." (PMID 24914548, 2014). "In our study, the results demonstrate for the first time the differential expression of CFTR and ENaC-α between the decidual tissue of abortion-prone and normal pregnant mice." (PMID 24914548, 2014). "In conclusion, increased CFTR expression and decreased ENaC-α expression in the decidua of early abortion may relate with failure of early pregnancy." (PMID 24914548, 2014). "So it would be interesting to determine whether functional interaction between CFTR and ENaC-α occurs in the decidual tissue of the CBA×DBA/2 mouse abortion model." (PMID 24914548, 2014). "We speculate that, in the decidual tissue from abortion-prone CBA mice, Th1-type cytokines might effects on Na+ absorption and Cl− secretion via alteration of the expression of CFTR and ENaC." (PMID 24914548, 2014).
acne (1 paper, 2025). An inflammatory process of the sebaceous glands which is characterized by comedones, nodules, papules and/or pustules on the skin. "Regarding known side effects of CFTR modulators, acne has been reported multiple times in the literature, but the underlying mechanisms remain unclear." (PMID 41209022, 2025).
acute leukemia (1 paper, 2017). A clonal (malignant) hematopoietic disorder with an acute onset, affecting the bone marrow and the peripheral blood. "In this study, we demonstrated the mean expression level of CFTR in Ph+ acute leukemia cells was markedly higher than that in Ph- B-ALL and CML-chronic phase cells." (PMID 28445932, 2017). "Our results demonstrated that CFTR expression was significantly higher in Ph+ acute leukemia cells than that in normal controls, Ph– B-ALL cells and CML-CP cells." (PMID 28445932, 2017). "In conclusion, our results showed CFTR was highly expressed in Ph+ acute leukemia, which protected and maintained the continuous activation of BCR-ABL and the canonical Wnt/β-catenin signaling pathway by decreasing PP2A phosphatase activity." (PMID 28445932, 2017). "First, CFTR expression is significantly higher in Ph+ acute leukemia cell lines and patient samples than in Ph– B-ALL and CML-chronic phase cells." (PMID 28445932, 2017). "We therefore hypothesize that CFTR may interact with PP2A—a bona fide tumor suppressor protein in Ph+ acute leukemia—to protect and maintain the continuous activation of BCR-ABL and related signaling pathways." (PMID 28445932, 2017). "In our study, we found that p-BCR-ABL and classical Wnt/β-catenin signaling were significantly down-regulated (i.e., Dvl-2 and β-catenin were significantly down-regulated and p-GSK3β was significantly up-regulated) when CFTR protein was reduced by CFTRinh-172 and shRNA in Ph+ acute leukemia cells." (PMID 28445932, 2017). "Second, high CFTR expression is crucial for the survival of Ph+ acute leukemia cells." (PMID 28445932, 2017). "Interestingly, our research showed that CFTR inhibited PP2A anti-tumor activity, revealing its central role in Ph+ acute leukemia." (PMID 28445932, 2017). "We therefore proposed a hypothesis: CFTR and PP2A interacted through a special domain or subunit in Ph+ acute leukemia cells." (PMID 28445932, 2017). "Finally, high CFTR expression inhibits the phosphatase activity of PP2A to protect and maintain the continuous activation of BCR-ABL and canonical Wnt/β-catenin signaling via the interaction with the PP2AA subunit in the cytosol of Ph+ acute leukemia cells." (PMID 28445932, 2017).
Af (1 paper, 2024). "In this Section, we have outlined the impact of CFTR modulators on CF-ABPA particularly focusing on the ABPA diagnostic biomarker IgE and Af infection and colonization." (PMID 39330416, 2024). "As CFTR therapy becomes increasingly prevalent in CF management, understanding its potential impact on ABPA, particularly on the allergic immune response pathways and Af infection becomes increasingly important for optimizing patient outcomes." (PMID 39330416, 2024).
alcoholic cirrhosis (1 paper, 2023). "By immunohistochemistry for Sct and immunohistochemistry/immunofluorescence for SR, CFTR and AE2 in human liver sections, there was increased immunoreactivity of Sct, SR, CFTR, and AE2 in patients with alcoholic cirrhosis compared to healthy control livers." (PMID 36624475, 2023).
allergic asthma (1 paper, 2025). A asthma with a basis in a pathological type I hypersensitivity reaction. "A small case series report has also linked non‐allergic asthma to abnormal CFTR function observed through nasal potential differences, providing a clue that defects in this pathway could be linked to the clinical phenotype of non‐eosinophilic asthma through a feedback mechanism." (PMID 39358991, 2025).
allergic rhinitis (1 paper, 2004). Inflammation of the nasal mucous membranes caused by an IgE-mediated response to external allergens. "The first case was a young boy who had been initially suspected of having CF at age 4 years because of allergic rhinitis but for whom the diagnosis of CF was later ruled out; no other CFTR sequence alteration could be identified and the sweat tests were negative (chloride values <40 mM)." (PMID 15287992, 2004).
anaphylaxis (1 paper, 2020). An acute hypersensitivity reaction that occurs from exposure to an allergen. "Anecdotally at our site, one case of suspected anaphylaxis occurred following the first dose of TEZ/IVA; no CFTR modulators have ever been retrialed in this patient." (PMID 33374882, 2020).
autonomic neuropathy (1 paper, 2016). An inherited or acquired peripheral neuropathy affecting the autonomic nervous system. "Given the expression of CFTR in the ENS together with the previously established CFTR expression in the sympathetic ganglia and paracervical ganglia, it is conceivable that malfunction of CFTR in the ganglionic neurons also contributes to the occurrence of autonomic neuropathy in CF." (PMID 27491544, 2016).
Bcc (1 paper, 2017). "The introduction of correctors and potentiators of the CFTR defects requires more studies of drug-drug interactions to predict treatment efficacy, however, this is not possible while a standard therapy for Bcc is not available." (PMID 28878751, 2017).
Becker muscular dystrophy (1 paper, 2025). Becker muscular dystrophy (BMD) is a neuromuscular disease characterized by progressive muscle wasting and weakness due to degeneration of skeletal, smooth and cardiac muscle. "In 5 couples, both partners have P/LP variants in the same AR gene (CFTR, GJB2, ATP7B, DHCR7), and in one couple, a woman has a clinically significant variant in the DMD gene linked to Becker muscular dystrophy." (PMID 41595422, 2025).
Brody myopathy (1 paper, 2025). Brody myopathy is a hereditary condition that affects the skeletal muscles (muscles used for movement). "Our aim now is to translate into therapy the use of the C17 CFTR corrector molecule to cure defective but functional SERCA1 proteins causing Brody myopathy." (PMID 41206505, 2025). "The knowledge of PMT pathogenesis, allowed us to propose a potential pharmacological approach to cure Brody myopathy, based on the repositioning strategy of ‘CFTR correctors’." (PMID 41206505, 2025). "In this study, using in vitro, in vivo and ex vivo experimental approaches, we investigated CFTR correctors specifically C17 molecule, as potential therapeutic candidate for Brody myopathy." (PMID 41206505, 2025).
cardiomyopathy (1 paper, 2019). A disease of the heart muscle or myocardium proper. "In term of heart; abnormal CFTR expression is found in the CF myocardium, Recently, the concept of early CF related cardiomyopathy has been suggested and include functional and inflammatory mechanisms." (PMID 31194748, 2019).
colon adenoma (1 paper, 2022). An adenoma that arises from the colon. "Moreover, it has been shown that inactivating mutations in CFTR gene increased the early incidence and progression of colon adenomas." (PMID 35216222, 2022).
colorectal adenoma (1 paper, 2021). An adenoma that arises from the colon or rectum. "SI-NETs were devoid of CFTR and WNT2 expression, whereas both genes were expressed in the adenocarcinomas and colorectal adenomas of the deletion carriers." (PMID 34274970, 2021).
congenital hypogonadotropic hypogonadism (1 paper, 2024). Congenital hypogonadotropic hypogonadism (CHH) is a rare disorder of sexual maturation characterized by gonadotropin (Gn) deficiency with low sex steroid levels associated with low levels of follicle stimulating hormone (FSH) and luteinizing hormone (LH). "The genetic investigations consist of karyotype, CFTR gene mutations plus variant of the IVS8-5T polymorphic trait, Y chromosome microdeletion, and Next Generation Sequencing panel to analyze genes implicated in congenital hypogonadotropic hypogonadism (CHH)." (PMID 39124666, 2024).
corneal edema (1 paper, 2025). "Recent data suggest that CFTR is an attractive target for corneal edema." (PMID 40864823, 2025).
Cough (1 paper, 2012). A sudden, audible expulsion of air from the lungs through a partially closed glottis, preceded by inhalation. "Regardless, our results indicate that individuals with sustained CFTR dysfunction are more predisposed to symptoms attributable to delayed mucociliary transport, including the severity of daily chronic cough independent of current cigarette smoking." (PMID 22768130, 2012).
craniosynostosis (1 paper, 2023). Craniosynostosis is defined as the premature fusion of one or more cranial sutures leading to secondary distortion of skull shape resulting in skull deformities with a variable presentation. "Epistatic interactions have been described for cystic fibrosis (CFTR) and DCNT4 or craniosynostosis (SMAD6) and BMP2 amongst others." (PMID 37477760, 2023).
diverticulosis (1 paper, 2015). "The muscular wall of the ileum and colon was thickened and more fragile in the CFTR-/- piglets with the presence of diverticulosis." (PMID 26600426, 2015).
dysplasia (1 paper, 2022). A usually neoplastic transformation of the cell, associated with altered architectural tissue patterns. "In 2020, Liu and colleagues reported that the deficiency of the CFTR gene leads to cardiac dysplasia during zebrafish embryogenesis and is associated with DCM." (PMID 36292100, 2022).
E. coli infection (1 paper, 2010). "One important observation made in this study is the upregulation of CFTR and CAII, along with several important inflammatory cytokines, upon E. coli-LPS challenge in vitro or E. coli infection in vivo." (PMID 21151921, 2010).
End Stage Liver Disease (1 paper, 2026). Final stage of a liver disease when the liver failure is irreversible and LIVER TRANSPLANTATION is needed. "Median model for end-stage liver disease-sodium scores were higher among individuals waitlisted following the approval of dual (9 vs 10, P < .013) and triple (9 vs 12.5, P < .003) CFTR modulators." (PMID 41362828, 2026). "Furthermore, a significant increase in the median model for end-stage liver disease-sodium (MELD-Na) scores was observed with the approval of dual (9 vs 10, P < .013) and triple (9 vs 12.5, P < .003) CFTR modulators." (PMID 41362828, 2026).
endometrial carcinoma (1 paper, 2022). A malignant tumor arising from the epithelium that lines the cavity of the uterine body. "Considering the role of CFTR in endometrial carcinoma cells and in the cervical epithelium, intensified screening for women with CF, compared with healthy women, may be reasonable, as well as routine HPV vaccination." (PMID 35042562, 2022). "However, compared with cells from normal endometrium, the expression of CFTR was significantly upregulated in endometrial carcinoma cells, which could result in increased proliferation and transfer of endometrial carcinoma cells." (PMID 35042562, 2022).
ependymoma (1 paper, 2024). A WHO grade II, slow growing tumor of children and young adults, usually located intraventricularly. "BST1, FLG, KANK4, and SHISA9 were significantly higher expressed in SP-EPN subtype A compared to all other ependymomas, whereas AK5, CFTR, RASSF6, and TBX22 showed high expression in subtype B." (PMID 38265489, 2024).
Failure to thrive (1 paper, 2019). Failure to thrive (FTT) refers to a child whose physical growth is substantially below the norm. "Altogether, both models exhibited failure to thrive but CFTR KO rats displayed a more severe nutritional and intestinal phenotype when compared to F508del animals." (PMID 31942562, 2019).
fluorosis (1 paper, 2025). "In particular, we noted increased CFTR-linked proteins, such as LDHA, UBA1, implying that the latter may play a role in fluorosis." (PMID 41000239, 2025).
fungal lung disease (1 paper, 2021). "In this review we discuss what impact novel CFTR modulators will have on fungal lung disease and its management in CF." (PMID 33813719, 2021). "An important question in this new era of CFTR modulators is what impact these drugs will have on fungal lung disease and its management in CF." (PMID 33813719, 2021).
gallbladder disease (1 paper, 2022). "Our data suggests that CF gallbladder disease may be mild because of CFTR’s minor role in liquid transport and the presence of multiple HCO3− secretion mechanisms." (PMID 35685290, 2022).
germ cell tumor (1 paper, 2016). A benign or malignant, gonadal or extragonadal neoplasm that originates from germ cells. "We chose NT2, a human germ cell tumor cell line to see whether knock down of CFTR affects the VDAC1 mediated pathway." (PMID 27483469, 2016).
glucose metabolic disorder (1 paper, 2017). "The present findings provide an alternative explanation for blood glucose metabolic disorder observed in PCOS via impaired glucagon production, as a result of hyperandrogenism-induced CFTR upregulation." (PMID 29204121, 2017).
Gorlin syndrome (1 paper, 2015).
hyperandrogenism (1 paper, 2017). Excessive secretion of androgens from the adrenal glands or gonads. "Given that hyperandrogenism is a hallmark of PCOS and that CFTR can be upregulated by androgen, we suspected that the suppressed glucagon in PCOS could be due to androgen-induced upregulation of CFTR." (PMID 29204121, 2017).
Hypercalcemia (1 paper, 2016). An abnormally increased calcium concentration in the blood. "On the basis of our current findings, we suggest that mutations, which affect expression and/or function of CFTR, would lead to a reduction of increases in fluid secretion induced by fetal hypercalcemia via CaSR activation." (PMID 26911344, 2016). "Together, these observations suggest that physiological fetal hypercalcemia, acting on the CaSR, promotes human fetal lung development via cAMP-dependent opening of CFTR." (PMID 26911344, 2016). "Here we demonstrate that fetal hypercalcemia, acting through the CaSR, promotes human fetal lung growth and expansion via CFTR." (PMID 26911344, 2016). "Together, these results suggest that physiological fetal hypercalcemia stimulates fluid secretion via the CaSR in the developing human lung, a process which does not occur in the developing mouse lung, where hypercalcaemia drives anion-driven fluid secretion through channels other than CFTR." (PMID 26911344, 2016).
hypersensitivity reaction (1 paper, 2020). "Rash and Hypersensitivity: If a patient experiences a rash or other hypersensitivity reaction secondary to a CFTR modulator, pharmacists can work with the healthcare team to appropriately manage based on the severity and confirmed or suspected diagnosis." (PMID 33374882, 2020).
Hypoalbuminemia (1 paper, 2014). The concentration of albumin in the blood circulation is below the lower limit of normal. "Hypoalbuminemia, decreased total protein, and increased blood urea nitrogen were observed in CFTR−/− rats." (PMID 24608905, 2014).
hypospadias (1 paper, 2022). Hypospadias is the displacement of the urethral meatus on the ventrum of the penis. "It is remarkable that neither CFTR nor ADGRG2 variants were identified in hypospadias/CAVD patients." (PMID 36437957, 2022).
immunodeficiency-21 (1 paper, 2025). "Among these, CFTR is the pathogenic gene for CF, GATA2 is associated with immunodeficiency-21, and the remaining 13 genes are associated with PCD." (PMID 40128832, 2025).
Impaired glucose tolerance (1 paper, 2020). An abnormal resistance to glucose, i.e., a reduction in the ability to maintain glucose levels in the blood stream within normal limits following oral or intravenous administration of glucose. "Therefore, whilst defective CFTR contributes to oxidative stress in CF, it is likely that the dysregulation of various inflammatory-redox cycles also exacerbates cellular damage and contributes to a worsened phenotype (e.g. the progression from impaired glucose tolerance to CFRD)." (PMID 32044291, 2020).
insulinoma (1 paper, 2021). "The importance of CFTR in insulin secretion has also been confirmed in a mouse insulinoma cell line, MIN6, where genetic or pharmacological inhibition of CFTR caused a reduction in insulin secretion that was further decreased in the presence of oxidative stress." (PMID 34566890, 2021).
intestinal infections (1 paper, 2025). "Conversely, older people with diminished CFTR function may experience less severe fluid loss and symptoms during acute intestinal infections, but may conversely be more prone to develop constipation." (PMID 40066329, 2025).
juvenile idiopathic arthritis (1 paper, 2023). Juvenile idiopathic arthritis (JIA) is the term used to describe a group of inflammatory articular disorders of unknown cause that begin before the age of 16 and last over 6 weeks. "Moreover, our experience suggests that anti-TNFα is an effective option in CF patients affected by juvenile idiopathic arthritis, and is even safe for children receiving a triple CFTR modulator." (PMID 36902517, 2023).
Kallmann syndrome (1 paper, 2024). Kallmann syndrome (KS) is a developmental genetic disorder characterized by the association of congenital hypogonadotropic hypogonadism (CHH) due to gonadotropin-releasing hormone (GnRH) deficiency, and anosmia or hyposmia (with hypoplasia or aplasia of the olfactory bulbs). "The pH of patients with CFTR gene mutations was significantly lower than in patients with Kallmann syndrome, with 47, XXY karyotype, chromosomal abnormalities, and Y microdeletion (p < 0.001)." (PMID 39124666, 2024). "Additionally, the volume of patients with CFTR gene mutations was significantly lower than those with Kallmann syndrome and Y Microdeletion (p < 0.001)." (PMID 39124666, 2024). "Gonadotrophin levels in patients with Kallmann syndrome were significantly lower than in patients with 47, XXY karyotype, Y microdeletion, and CFTR gene mutations (p < 0.001)." (PMID 39124666, 2024). "Testosterone value was significantly lower in patients with Kallmann syndrome than in patients with 47, XXY karyotype, Y microdeletion, CFTR gene mutations, and chromosomal abnormalities (p < 0.05)." (PMID 39124666, 2024).